GTPBP4 (GTP binding protein 4)
Description:
Involved in the biogenesis of the 60S ribosomal subunit.
Synonyms: CRFG; NOG1; NGB; FLJ10690; FLJ10686
Tractability: Small molecule: a structure with a bound ligand is known. PROTAC: UniProt records ubiquitination sites on it; ubiquitination databases record sites on it; its protein half-life has been measured; a small molecule that binds it is known.
Gene: Protein-coding gene on chromosome 10 (988,418 to 1,019,932, forward strand). Ensembl gene ENSG00000107937.
Subcellular location: Nucleus, nucleolus
Subcellular location (Human Protein Atlas): Nucleoli; Nucleoli rim; Nuclear membrane
Gene Ontology:
Molecular function: GTP binding; GTPase activity; preribosome binding; protein binding; RNA binding
Biological process: negative regulation of cell migration; negative regulation of cell population proliferation; negative regulation of cell-cell adhesion; negative regulation of DNA replication; negative regulation of G2/M transition of mitotic cell cycle; negative regulation of protein ubiquitination; osteoblast differentiation; protein stabilization; ribosomal large subunit biogenesis; ribosome biogenesis
Cellular component: cytoplasm; membrane; nucleolus; nucleus; perinuclear region of cytoplasm
Genetic constraint (gnomAD): Loss-of-function variants: 4 observed, 22.58 expected, observed/expected ratio (o/e) 0.18, 90% interval 0.086 to 0.41. The upper end of that interval is the gene's LOEUF score, 0.41, which puts it in group 1 of 6, group 1 being the genes least tolerant of losing a copy. Missense variants: 338 observed, 315.69 expected, observed/expected ratio (o/e) 1.07, 90% interval 0.98 to 1.17. Synonymous variants: 122 observed, 116.06 expected, observed/expected ratio (o/e) 1.05, 90% interval 0.91 to 1.22.
Homologues: Orthologues: guinea pig GTPBP4 (95% identical), mouse Gtpbp4 (95% identical), dog GTPBP4 (94% identical), pig GTPBP4 (92% identical), macaque GTPBP4 (91% identical), tropical clawed frog gtpbp4 (83% identical), zebrafish gtpbp4 (83% identical), chimpanzee GTPBP4 (74% identical), Drosophila melanogaster Non1 (61% identical), rat Gtpbp4 (58% identical), Caenorhabditis elegans nog-1 (57% identical). Paralogues in human: GTPBP10 (13% identical), DRG2 (12% identical), DRG1 (12% identical), MTG2 (12% identical).
Diseases named in the same sentence as GTPBP4 in open-access papers:
GTPBP4 is named in the same sentence as 24 diseases in open-access papers, as found by Europe PMC text mining. Sharing a sentence is not in itself a finding about the gene and the disease. The quoted sentences say what the papers report.
hepatocellular carcinoma (9 papers, 2017 to 2023). A malignant tumor that arises from hepatocytes. "Whether the expression level of GTPBP4 in hepatocellular carcinoma (HCC) is associated with the patients’ prognosis or its function and underlying molecular mechanisms still remains unclear." (PMID 29212203, 2017). "It was demonstrated that GTPBP4 promoted hepatocellular carcinoma (HCC) growth and metastasis both in vivo and in vitro and promoted aerobic glycolysis by inducing dimeric pyruvate kinase M2 (PKM2) formation." (PMID 38098990, 2023). "Since GTPBP4 has been reported as being of extreme significance in hepatocellular carcinoma, we further studied the transcription factors of GTPBP4." (PMID 35320117, 2022). "For example, the high expression of GTPBP4 is a poor prognostic factor for clear cell renal cell carcinoma and hepatocellular carcinoma (P < 0.05)." (PMID 35320117, 2022). "In this study, multivariate Cox regression was used to construct a prognostic biomarker model of hepatocellular carcinoma consisting of two protein-coding genes (GTPBP4, TREM-1) and one lncRNA (LINC00426)." (PMID 33204302, 2020). "Meanwhile, patients with HCC (hepatocellular carcinoma) with high levels of GTPBP4 expression tended to have a poor prognosis." (PMID 33134380, 2020). "Knockdown of GTPBP4 gene in hepatocellular carcinoma (HCC) inhibited cell proliferation, impaired colony formation ability, induced cell cycle arrest in G2/M period, and promoted apoptosis in HCC cell lines." (PMID 36405249, 2022). "The involvement of GTPBP4 in BLCA’s development has not been characterized, but oncogenic properties have been attributed to this gene in hepatocellular carcinoma." (PMID 35626146, 2022).
breast carcinoma (8 papers, 2013 to 2022). "The findings revealed that elevated GTPBP4 expression was linked to a poor breast cancer outcome (p = 0.012)." (PMID 35784753, 2022). "To begin, we discovered that GTPBP4 expression was upregulated in breast cancer, which was confirmed by multiple cohorts." (PMID 35784753, 2022). "The activity, migration, and proliferation of breast cancer cells were considerably reduced after GTPBP4 knockdown in the CCK-8, Transwell, and Scratch assays." (PMID 35784753, 2022). "We created a nomogram integrating GTPBP4 expression and clinical features to further evaluate the survival of breast cancer patients." (PMID 35784753, 2022). "In our study, GTPBP4, a novel biomarker, was discovered, which has significant significance for us to evaluate the prognosis of breast cancer patients and to understand the immune microenvironment." (PMID 35784753, 2022). "In this study, the expression, prognostic significance, and immunological connection of GTPBP4 in breast cancer were investigated." (PMID 35784753, 2022). "According to the median expression value of GTPBP4, TCGA breast cancer patients were separated into two groups: high expression and low expression." (PMID 35784753, 2022). "Then we look at the role of GTPBP4 in the immune milieu and create a Nomogram to help patients with breast cancer understand their prognosis." (PMID 35784753, 2022). "To begin, we analyzed the TIMER and UALCAN databases to see if there was a difference in GTPBP4 expression between breast cancer and normal tissues." (PMID 35784753, 2022). "To confirm GTPBP4 expression in breast cancer, we looked at it in multiple independent cohorts, including one TCGA cohort and five GEO cohorts." (PMID 35784753, 2022). "GTPBP4 was found to be an independent breast cancer prognostic factor in subsequent survival analyses." (PMID 35784753, 2022). "It was reported that in lung adenocarcinoma, colorectal cancer, and breast cancer, GTPBP4 showed a trend of upregulated expression." (PMID 34712323, 2021). "For example, aberrantly expressed GTPBP4 was found to be significantly associated with low survival probability in patients with HCC and breast cancer." (PMID 33134380, 2020). "The importance of GTPBP4 in breast cancer was investigated in this study." (PMID 35784753, 2022). "GTPBP4 expression upregulation in breast cancer is thus plausible." (PMID 35784753, 2022). "GTPBP4 has a high diagnosis accuracy for breast cancer, according to these findings." (PMID 35784753, 2022). "This is significant for revealing the role of GTPBP4 in breast cancer." (PMID 35784753, 2022). "PCR assay showed that GTPBP4 expression was up-regulated in breast cancer cell lines." (PMID 35784753, 2022). "Finally, in vitro tests were carried out to look at GTPBP4 expression and function in breast cancer cell lines." (PMID 35784753, 2022). "The predictive effect of GTPBP4 in breast cancer was then assessed using survival analysis." (PMID 35784753, 2022). "Using a variety of approaches, we assessed the importance of GTPBP4 in breast cancer." (PMID 35784753, 2022). "Recent studies have reported that the observed decrease in the expression of GTPBP4 could inhibit the proliferation of human colon cancer cells, while its increased expression was related to a decreased survival rate in colon and breast cancer patients." (PMID 35706452, 2022). "In addition, we also identified 5 immune cell types most closely related to GTPBP4, which is not only beneficial to our understanding of the function of GTPBP4 but also helpful to explore the immune microenvironment of breast cancer." (PMID 35784753, 2022). "The relative expression levels of GTPBP4 in Breast Cancer cell lines were quantified using qRT-PCR." (PMID 35784753, 2022).
breast carcinoma (continued). "In addition, high expression of GTPBP4 is significantly correlated with reduced survival in breast cancer, colorectal carcinoma and HCC." (PMID 33411682, 2020). "Furthermore, breast cancer patients with a high expression of GTPBP4 exhibited a short survival time." (PMID 33204302, 2020). "Second, we discovered that GTPBP4 may accurately diagnose breast cancer." (PMID 35784753, 2022). "GTPBP4’s significance in breast cancer, however, is unknown." (PMID 35784753, 2022). "In addition, depletion of GTPBP4 could inhibit cell proliferation, and high expression correlated with a worse prognosis than the low expression of GTPBP4 in breast cancer." (PMID 35875102, 2022). "With three different siRNA sequences, we inhibited the expression of GTPBP4 in ZR-75-1 and MDA-MB-231 breast cancer cell lines using RNAi technology." (PMID 35784753, 2022). "Because GTPBP4 expression was higher in the ZR-75-1 and MDA-MB-231 breast cancer cell lines, gene knockdown was performed in these two cell lines." (PMID 35784753, 2022).
colorectal cancer (8 papers, 2017 to 2023). A primary or metastatic malignant neoplasm that affects the colon or rectum. "GTPBP4 has shown superior diagnostic and survival effects through human colorectal cancer survival analysis and diagnostic tests." (PMID 38098990, 2023). "A number of recent studies have shown that GTPBP4 is associated with the cell proliferation of gastric cancer, the prognosis of liver cancer patients, and the spread of colorectal cancer." (PMID 36405249, 2022). "On the other hand, some studies found that GTPBP4, as an oncogene, was upregulated in breast and colorectal cancer and high level of GTPBP4 was closely associated with unfavorable prognosis of these patients." (PMID 29212203, 2017). "GTPBP4 mediates ribosomal RNA processing, suppresses schwannoma cell growth, and promotes colorectal carcinoma metastasis in vitro." (PMID 35248088, 2022). "According to reports, in colorectal cancer, GTPBP4 can weaken the activity of RhoA to destroy the skeleton of actin and promote the metastasis of cancer cells." (PMID 34712323, 2021). "In colorectal cancer, GTPBP4 was demonstrated as an oncogene that could disrupt the actin cytoskeleton and promote metastasis of cancer." (PMID 35875102, 2022). "A study of colorectal carcinoma (CRC) also uncovered that GTPBP4 was responsible for tumor metastasis." (PMID 33134380, 2020).
liver cancer (4 papers, 2021 to 2022). An epithelial or non-epithelial malignant neoplasm that arises from the liver. "GTPBP4 has now been described as having a possible role in the development of cancer, particularly liver cancer." (PMID 35320117, 2022). "We used cell experiments to explore the effects of overexpression and underexpression of GTPBP4 on liver cancer cells." (PMID 34712323, 2021). "This indicates that GTPBP4 is not only related to immune cell invasion, affecting the prognosis of liver cancer patients, but also directly affects the proliferation of liver cancer cells, promoting the development of liver cancer." (PMID 34712323, 2021). "The upregulated expression of GTPBP4 promotes the proliferation of liver cancer cells and the growth of tumors." (PMID 34712323, 2021). "In order to further explore the effect of GTPBP4 on liver cancer cells in vivo, we conducted the nude mouse tumorigenicity assay." (PMID 34712323, 2021). "This study explored the expression of GTPBP4 gene in liver cancer patients and its prompting effect on the prognosis of liver cancer patients in GEPIA2, Kaplan–Meier plotter, and other databases." (PMID 34712323, 2021). "Through the CCK-8 experiment, the effect of GTPBP4 gene expression on the growth of liver cancer cells was explored." (PMID 34712323, 2021). "Liver cancer patients with upregulated expression of GTPBP4 showed a shorter overall survival rate (P=0.02)." (PMID 34712323, 2021). "The overall survival rate results showed that liver cancer patients with downregulated expression of GTPBP4 had a better overall survival rate." (PMID 34712323, 2021). "In order to observe the expression of GTPBP4 in liver cancer patients and the overall survival of liver cancer patients with different expression levels of GTPBP4, we searched GTPBP4 in various online databases." (PMID 34712323, 2021). "In order to verify the effect of GTPBP4 gene on the proliferation of liver cancer cells in vivo and in vitro, this study conducted CCK-8 experiments and nude mouse tumorigenicity assay." (PMID 34712323, 2021). "The expression of GTPBP4 is upregulated in liver cancer patients and affects the overall survival rate of patients." (PMID 34712323, 2021). "The upregulated expression of GTPBP4 will reduce the overall survival rate of liver cancer patients." (PMID 34712323, 2021). "In summary, this study found that GTPBP4 is highly expressed in liver cancer patients and is significantly related to the degree of lymph node metastasis through our exploration of public databases." (PMID 34712323, 2021). "This study found that GTPBP4 had an upregulated expression in liver cancer patients by mining public databases (P < 0.01), and its expression level increased with the increase of cancer metastasis in lymph nodes (P < 0.01)." (PMID 34712323, 2021). "Subsequently, the expression of the mRNA level and protein level of the GTPBP4 gene in liver cancer cells was verified by fluorescence quantitative PCR and Western blotting experiments." (PMID 34712323, 2021). "Therefore, this study takes GTPBP4 as the main research object, which can make some explorations for its research in liver cancer." (PMID 34712323, 2021). "The results showed that GTPBP4 had a high expression in liver cancer patients (P < 0.01)." (PMID 34712323, 2021). "In addition, we also found that liver cancer patients with upregulated expression of GTPBP4 showed a shorter overall survival time (P=0.02), which is consistent with the results of previous studies." (PMID 34712323, 2021). "The results of cell proliferation experiments showed that overexpression of GTPBP4 could promote the proliferation of liver cancer cells and that inhibiting the expression of GTPBP4 could also inhibit the proliferation of liver cancer cells." (PMID 34712323, 2021).
liver cancer (continued). "The upregulated expression of GTPBP4 promotes the proliferation of liver cancer cells and promotes the growth of tumors in mice, while the downregulated expression of GTPBP4 inhibits the proliferation of liver cancer cells and inhibits the growth of tumors in mice." (PMID 34712323, 2021). "The expression of GTPBP4 was positively correlated with the invasion of B cells and macrophages, which may be one of the reasons why the expression of GTPBP4 can affect the overall survival time of liver cancer patients." (PMID 34712323, 2021). "Eventually, a four-gene (karyopherin subunit alpha 2(KPNA2), suppressor of cytokine signaling 2(SOCS2), GTP-binding protein 4(GTPBP4), and chromobox 2(CBX2)) signature model was constructed by multivariate analysis showing that they were independent prognostic factors for liver cancer." (PMID 35479398, 2022). "However, this study still has some shortcomings, that is, it failed to test the signal pathway of GTPBP4 gene affecting the proliferation of liver cancer cells." (PMID 34712323, 2021).
lung adenocarcinoma (4 papers, 2020 to 2022). A carcinoma that arises from the lung and is characterized by the presence of malignant glandular epithelial cells. "The mechanism by which GTPBP4 regulation affects the progression of lung adenocarcinoma may be related to the regulation of EMT." (PMID 36405249, 2022). "The results showed that GTPBP4 was highly expressed in lung adenocarcinoma cell lines compared with the control group (normal human embryonic lung cell MRC-5), and GTPBP4 was the highest expression in A549 cells." (PMID 36405249, 2022). "However, there have been no prior reports regarding the expression or the role of GTPBP4 in lung adenocarcinoma." (PMID 33134380, 2020).
gastric cancer (3 papers, 2020 to 2023). A primary or metastatic malignant neoplasm involving the stomach. "When the eight characteristic genes (ENTPD3, PDZD4, CNN1, GTPBP4, FPGS, UTP25, CENPW, and FAM111A) are all fitted into one variable, the AUC of the ROC curve is 0.996, indicating a good diagnostic efficiency for gastric cancer." (PMID 37007099, 2023). "We have established the early diagnosis model of eight characteristic genes (ENTPD3, PDZD4, CNN1, GTPBP4, FPGS, UTP25, CENPW, and FAM111A) for gastric cancer." (PMID 37007099, 2023).
melanoma (3 papers, 2020 to 2022). A malignant, usually aggressive tumor composed of atypical, neoplastic melanocytes. "The GTP-binding protein 4 (GBP4) was previously identified as a prognostic signature gene that separates melanoma patients into low- and high-risk groups according to survival." (PMID 36135194, 2022). "Besides, the researchers also found that GTPBP4 gene mutations could promote the proliferation of melanoma cells, and the expression of GTPBP4 was also closely related to the clinical stage of bladder cancer, cancer metastasis, and the overall survival time of patients after surgery." (PMID 34712323, 2021).
breast tumors (2 papers, 2014 to 2017).
colon cancer (2 papers, 2022). "Only HSP90AB1, RIPK2, DDX21, UCHL5, GTPBP4, and PCID2 were significantly different in UC and COAD tissues, and they all showed overexpression in colon cancer tissues compared to UC tissues." (PMID 35372018, 2022).
glioma (2 papers, 2017 to 2022). A benign or malignant brain and spinal cord tumor that arises from glial cells (astrocytes, oligodendrocytes, ependymal cells). "Recently, studies reported that in glioma cell lines, GTPBP4 inhibited cell proliferation by regulating Merlin protein and CyclinD1 protein." (PMID 36405249, 2022).
viral infection (2 papers, 2023 to 2024). "Although GTPBP4 has multiple biological functions, its role in viral infection is still not fully understood." (PMID 38516932, 2024). "Mechanically, FMDV VP1 promotes autophagy during virus infection and interacts with and degrades YTHDF2 (YTH N6-methyladenosine RNA binding protein F2) in an AKT-MTOR-dependent autophagy pathway, resulting in an increase in GTPBP4 mRNA and protein levels." (PMID 38516932, 2024).
Cirrhosis (1 paper, 2017). A chronic disorder of the liver in which liver tissue becomes scarred and is partially replaced by regenerative nodules and fibrotic tissue resulting in loss of liver function. "We evaluated the association between GTPBP4 protein expression and clinicopathological characteristics of HCC patients, including age, gender, Edmondson classification, tumor size, vascular invasion, cirrhosis and TNM stage." (PMID 29212203, 2017).